Y_RNA (Y RNA )
Gene: Miscellaneous RNA gene on chromosome 2 (206,025,593 to 206,025,697, forward strand). Ensembl gene ENSG00000207386.
Homologues: Orthologues: chimpanzee Y_RNA (100% identical), macaque Y_RNA (92% identical), guinea pig Y_RNA (90% identical). Paralogues in human: Y_RNA (89% identical), RNY3 (88% identical), Y_RNA (88% identical), Y_RNA (87% identical), Y_RNA (86% identical), RNY3P1 (85% identical), RNY3P16 (85% identical), Y_RNA (85% identical), RNY3P4 (84% identical), Y_RNA (84% identical), RNY3P9 (83% identical), Y_RNA (83% identical), and 96 more.